TNF (tumor necrosis factor)
Diseases named in the same sentence as TNF in open-access papers (continued):
Sharing a sentence is not in itself a finding about the gene and the disease.
Insulin resistance (continued). "Pro-inflammatory cytokines, such as TNF-α and IL6, stimulate both the c-Jun N-terminal kinase (JNK) and IκB kinase-β (IKK-β)/nuclear factor-κB (NF-κB) pathways, resulting in upregulation of potential mediators of inflammation that can lead to insulin resistance." (PMID 31866871, 2019). "Inflammatory cytokines secreted by adipose tissue, such as interleukin 6 (IL-6) and tumor necrosis factor alpha (TNF-α), may exert an endocrine effect to promote insulin resistance by interfering with the insulin signalling pathway, leading to the clinical manifestation of T2DM." (PMID 31485456, 2019). "While the M1 phenotype stimulates the generation of inflammatory cytokines such as TNF-α, iNOS, CCR2, and IL-12, the M2 phenotype promotes anti-inflammatory cytokines like IL-4 and IL-13, which relieve inflammatory reactions and inhibit the development of insulin resistance." (PMID 31212747, 2019). "Assessing the inflammatory background main actors in psoriasis and NAFLD, many proinflammatory cytokines, such as IL-1β, TNF-α, and IL6, are in common and may create, sustain, and maintain the three stages of NAFLD, namely, inflammation, insulin resistance, and lipid accumulation." (PMID 29546055, 2018). "Thus, we demonstrated that short-term exposure to 10 ng/ml TNFα induces reversible downregulation of IRS2 and eNOS due to EndMT-like differentiation and it is also likely to induce irreversible GM1 expression, probably resulting in chronic insulin resistance." (PMID 29464018, 2018). "Notably, it seems that vitamin D, the ligand of VDR, is not required for the role of VDR in glucocorticoid and TNFα induced insulin resistance." (PMID 30310815, 2018). "Our data suggested that SXT could suppress the activation of IKKβ/NF-κB signal pathway in liver and decrease the CRP, TNF-α, IL-6, and IL-1β levels in serum of T2DM rats, which were corresponding with the results that insulin resistance was markedly ameliorated in SXT-treated diabetes rats." (PMID 30210342, 2018). "In spite of those promising findings, TNF-α blockade was not effective in treating insulin resistance in obese patients, such findings that were somehow expected considering that inflammation is a complex process characterized by the involvement of many protein and lipid mediators." (PMID 30116154, 2018). "We evaluated serum high sensitivity C reactive protein (hsCRP), tumor necrosis factor alpha (TNF-α), chemerin, nitrite and nitrate (NOx), total oxidant status (TOS), total antioxidant response (TAR), fasting blood glucose, insulin, and homeostasis model assessment of insulin resistance (HOMA-IR)." (PMID 30200422, 2018). "However, in the setting of muscular release, it is known to induce anti-inflammatory effects with inhibition of TNF-α production and may thus prevent TNF-α-induced insulin resistance." (PMID 30008613, 2018). "During diabetes, an increased level of TNF-α showed the effect on the insulin receptor and decreased the insulin sensitivity, while IL-6 shows the effect on the glucose via altering the insulin receptor, IRS, glut-4, which increase the incidence of insulin resistance." (PMID 35542112, 2018). "Increased circulating levels of TNF-α and IL-6 augment the activity of 11β-HSD-1 resulting in an increase in the production of corticosterone in the adipose tissue, which can lead to abdominal obesity characteristically seen in Indians and those with insulin resistance and type 2 DM." (PMID 28824543, 2017). "TNF-α is highly involved with macrophage activation and increased serum TNF-α level have been observed in insulin resistance stages and diabetes mellitus development, however, inconsistency still existed and no meta-analysis was conducted about the change of serum TNF-α level in T1DM patients." (PMID 28426801, 2017).
Insulin resistance (continued). "Our observations of higher LPS, CRP, TNF-α/IL-10 ratio, and HOMA-IR values in the omnivorous group reinforce previous hypothesis that a saturated fat-enriched diet could induce inflammation and insulin resistance." (PMID 28814977, 2017). "Cytokines and chemokines, such as tumor necrosis factor alpha (TNF-α) and interleukin-1 beta (IL-1β), produced by adipose tissue macrophages (ATMs) in an M1 pro-inflammatory state have been identified as crucial effectors in the initiation of inflammation and the development of insulin resistance." (PMID 28515792, 2017). "Therefore, increased TNF-α and/or IL-6 secretion could explain the relationship between elevated serum hs-CRP and insulin resistance." (PMID 28575103, 2017). "Interestingly, TNF expression in SAT after bariatric surgery is independent of whole-body insulin resistance, contrary to the obese state." (PMID 27900559, 2017). "However, not all insulin resistance-related proinflammatory cytokines were different in this study as TNFα and IL-6 were similar in NR and RR mice." (PMID 27577172, 2016). "Moreover, some reports described that deletion or lacking of TNF-α gene allowed the protection against the development of insulin resistance in obese mice." (PMID 25789857, 2015). "Inflammatory cytokines, such as TNF-α, IL-6, and IL-8, are involved in the second hit stage, mediate steatohepatitis in patients with NAFLD, and can be regulated by PPARγ, which is not only related to anti-inflammatory effects, but also close to improving insulin resistance." (PMID 26221176, 2015). "Increased TNF-α and leptin may also be predictive, but studies must firmly establish their role independent of BMI and insulin resistance." (PMID 26110385, 2015). "Glucose uptake and consumption were improved in the rapamycin plus TNF-α or IL-6 groups compared with cells treated with TNF-α or IL-6 alone in the absence and presence of insulin, suggesting that rapamycin ameliorates inflammatory stress-induced insulin resistance in vitro." (PMID 26449763, 2015). "It was reported that TNF-α can increase glucose uptake in both visceral and subcutaneous adipocytes by activating the adenosine monophosphate activated protein kinase (AMPK) pathway, whereas it triggers insulin resistance in visceral adipocytes by activating JNK1/2." (PMID 26136779, 2015). "Thus far, TNF appears not to be a promising drug target, at least for the treatment of insulin resistance in humans." (PMID 25918733, 2015). "Moreover, a number of the genes such as proinflammatory genes of TNFα, IL6 and COCS3, which were increased in the muscle of hypertensive DS rats, have been shown to play a fundamental role in the pathogenesis of insulin resistance and T2DM." (PMID 25928697, 2015). "In addition, TNF-α does not induce insulin resistance when IL-6 is down-regulated in adipose tissue." (PMID 24733068, 2014). "Increases in TNF-α and SOCS3 are triggered by high glucose and through reciprocal stimulation of the expression of these two factors, which in turn could be major drivers of insulin resistance and related cell death." (PMID 25352752, 2014). "TNF-α may be a biomarker of insulin resistance rather than systemic inflammation in the present study as well." (PMID 25105150, 2014). "Taken together, these findings suggest that TNF-α- may be a biomarker of insulin resistance rather than systemic inflammation in our elderly women." (PMID 25105150, 2014). "Increases in TNF-α and SOCS3 are triggered by high glucose and through reciprocal stimulation of expression of these two factors, which in turn could be major drivers of insulin resistance and related cell death." (PMID 25352752, 2014). "Other adipokines, such as tumor necrosis factor (TNF-α), interleukin (IL)-6, IL-1β and monocyte chemoattractant protein (MCP)-1, are inflammatory cytokines which are suggested to participate in low-grade pro-inflammatory processes leading to metabolic disorders, insulin resistance, and CVDs." (PMID 25277804, 2014).
Insulin resistance (continued). "Some studies suggest that the ability of ALA supplementation in preventing insulin resistance might be related in part to the stimulation of AMPK and adiponectin in white adipose tissue and attenuation of monocyte chemokine protein 1 (MCP-1) and TNF-α." (PMID 25104975, 2014). "Previously, it was demonstrated that a short infusion of anti-TNF-α monoclonal antibodyinfliximab induced a rapid and dramatic reduction in serum insulin levels and insulin resistance along with a rapid improvement of insulin sensitivity in nondiabetic AS patients." (PMID 24757680, 2014). "Interestingly, TNF-α and neutrophil granulocytes still accounted for the degree of insulin resistance in the adult but not in the adolescent group." (PMID 24454366, 2013). "Furthermore, in a study implementing the TNFα cytokine, it was suggested that JNK might be the mediator to ROS-induced insulin resistance." (PMID 24324517, 2013). "Insulin resistance leads to a perturbation in the lipid homeostasis, cytokines, and adipokines production, resulting in increased systemic inflammation, with higher levels of inflammatory markers such as C-reactive protein (CRP), interleukin (IL)-6, and tumor necrosis factor (TNF)-α." (PMID 23762872, 2013). "Furthermore, insulin resistance occurs as a result of placental hormones that antagonize insulin, estrogen, progesterone, human placental lactogen (HPL), human placental growth hormone, cortisol, prolactin, and tumor necrosis factor-alpha (TNF-α)." (PMID 22518122, 2012). "The results demonstrating the close relationship between HOMA index and TLR2 expression in monocytes and inflammatory cytokines such as TNF-α and IL-6 could provide therapeutic interventions against insulin resistance in nondiabetic RA patients." (PMID 23213270, 2012). "These bioactive molecules, including leptin, adiponectin, visfatin, omentin, tumor necrosis factor-α (TNF-α), resistin, retinol-binding protein 4 (RBP4) and many others influence metabolic processes such as food intake, glucose- and lipid-metabolism, inflammation and insulin resistance." (PMID 22389718, 2012). "Therefore, hypothetically it is possible that TNF-α actually induces impaired glucose metabolism, while high systemic levels of IL-6 reflect a high local production of TNF-α and are not directly involved in the pathogenesis of insulin resistance." (PMID 22272193, 2012). "However, plasma insulin levels were increased, therefore suggesting the development of insulin resistance, even in the absence of TNFα." (PMID 23125848, 2012). "Surprisingly, theinfusion of anti-TNF-α antibody in humans did not affect insulin resistance." (PMID 18604303, 2008). "• TNFα, and resistin do not predict stress induced insulin resistance in our model." (PMID 19087258, 2008). "Both the treatments did not affect plasma TNF-α levels or insulin resistance status (HOMA-IR)." (PMID 17937812, 2007). "Interestingly, in our experimental conditions, CXCR1/2 inhibition in the insulin resistance model (TNF-a+LAD + INS) showed a behavior close to control (CTR + INS), thus suggesting CXCR1/2-mediated ameliorations in the pathways related to glucose uptake and insulin resistance." (PMID 39627194, 2024). "Notably, other cytokines, such as TNF-α and IL-6, known for their important role in insulin resistance, were not detectable in most enrolled subjects, so could not be included in the analysis." (PMID 37628530, 2023). "In addition, it has been shown that both TNF-α and dexamethasone could significantly inhibit the biological activity of insulin receptor tyrosine kinase, which subsequently facilitated the insulin resistance without influencing the translocation of GLUT4." (PMID 34784266, 2022).
Insulin resistance (continued). "Previous studies revealed that the production of lipid metabolites (diacylglycerol), proinflammatory cytokines (TNF-a, IL-1b, IL-6, monocyte chemoattractant protein-1) and cellular stress, including oxidative and endoplasmic reticulum stress, may contribute to FFA-induced insulin resistance." (PMID 35711703, 2022). "Furthermore, yam polysaccharides could reduce the levels of LDL-C and total TC, inhibit the production of SFAs, reduce the levels of IL-1β and TNF-α in serum, and down regulate the expression levels of MMP-3 protein in visceral adipose tissue to improve insulin resistance and reduce blood lipids." (PMID 36159471, 2022). "For example, TNF-activated signaling molecules such as IKK, JNK, S6 kinase, and mammalian target of rapamycin (mTOR) could potentially phosphorylate insulin receptor substrate 1 (IRS1) to attenuate insulin signaling and subsequently contribute to the development of insulin resistance." (PMID 33150865, 2020). "Increased release of tumor necrosis factor‐∞ (TNF‐∞), interleukin‐6 (IL‐6), monocyte chemoattractant protein‐1 (MCP‐1), and additional products of macrophages and other cells that populate adipose tissue might also have a role in the development of insulin resistance." (PMID 33191653, 2020). "These ameliorative effects could be related to the improvement of insulin resistance, suppression of oxidative stress and inflammation through mitigation of LPO, restoration of anti-oxidant enzymes (activity & mRNA), and the decreased TNF-α mRNA level and MPO activity." (PMID 32695286, 2020). "Also, they could improve the composition of gut microbiota and intestinal integrity as well as suppress the production of proinflammatory mediators such as interleukin-6 (IL-6) and tumor necrosis factor-α (TNF-α), and therefore may reduce inflammation, oxidative stress and insulin resistance." (PMID 31827628, 2019). "Yangyinqingre formula decreased serum glucose, insulin resistance, serum creatinine, and proteinuria in DKD models, and this renoprotection function could be related to its action in anti-inflammation, which involves inhibition of expression of TNF-α, IL-17, VEGF and CRP." (PMID 31281401, 2019). "Therefore, not only therapies targeting eNOS and/or TNFα, but also extracellular therapeutic strategies targeting GM1 may be useful for prevention and cure of vascular insulin resistance, although further studies are required to evaluate the effects of GM1 systemic targeting." (PMID 31013778, 2019). "Interestingly, TNF-alpha failed to induce insulin resistance in MC-T." (PMID 29968746, 2018). "Since phosphorylation status of Akt in the liver was altered in the fructose-fed mice wild-type mice and not the TNF-α knockout mice, it was concluded that TNF-α and its receptor 1 may be critical in mediating insulin resistance in the mice chronically fed fructose." (PMID 28555043, 2017). "Furthermore, some well-known pathogenic pro-inflammatory mediators in RA, such as interleukin-1β (IL-1β) and tumor necrosis factor (TNF), may play a pivotal role in the development of T2D, contributing to beta-cells disfunction and distruction and insulin resistance as observed in bone damage." (PMID 28704564, 2017). "Nevertheless, the concentration of IL-6 and TNF-α showed a non-significant trend to increased values in the O group compared to C. Vitamin E supplementation managed to reduce the concentration of both cytokines, which suggests that hepatic inflammation is not responsible for insulin resistance." (PMID 29028831, 2017). "However, in obese Zucker rats, anti-TNF treatment did not affect insulin resistance." (PMID 25918733, 2015). "Our findings of increased TNFα and SOCS3 in retinal endothelial and Müller cells under high glucose conditions agree well with findings in other cell types, including adipocytes and smooth muscle cells, suggesting that these retinal cells may also undergo a form of insulin resistance." (PMID 24695399, 2014).
Insulin resistance (continued). "Thus, ceramide has been regarded as mediator linking several metabolic stresses (i.e., TNF-α and saturated fatty acids, but not unsaturated fatty acids) to the induction of insulin resistance, although the role of TNF-α in insulin resistance is somewhat controversial." (PMID 24733068, 2014). "However, the correlation between plasma TNF-α levels and insulin resistance is relatively weak, and chronic neutralization of TNF-α does not improve insulin resistance in healthy overweight subjects with metabolic syndrome and insulin resistance, despite improvements in inflammatory status." (PMID 24733068, 2014). "With elevated levels of TNF-α being shown to cause a spectrum of negative effects, it was proposed that neutralization or deletion of genes coding for TNF-α receptors could possibly improve both adiposity and insulin resistance." (PMID 25309775, 2014). "Given that EPO treatment inhibits the NF-κB, ERK and JNK activation, and TNF-α and IL-6 production in animal models of hepatic injury, we hypothesize that EPO may also inhibit the HFD-induced chronic inflammation, contributing to the improvement of glucose intolerance and insulin resistance." (PMID 23326455, 2013). "Notably, the production of TNF-α in the culture supernatant that could affect insulin resistance was not significantly different among the three strains." (PMID 22383967, 2012). "Inflammatory mediators, such as pro-inflammatory cytokines (TNF-α, IL-1β, and IL-8) as well as anti-inflammatory cytokines (IL-10 and TGF-β), can induce insulin resistance without affecting lipid breakdown." (PMID 40231066, 2025). "Compared to IL-6 and TNF-α, which indicate chronic inflammation, SHBG is a negative marker that is it decreases, worsening insulin resistance and hyperandrogenism." (PMID 40385768, 2025). "Other markers of inflammation including TNF alpha have been reported in non-obese women with PCOS, though again without accounting for insulin resistance." (PMID 36079796, 2022). "In an Italian study, IL-6 was found to be significantly increased in all insulin-resistant PCOS, independent of BMI, but there was no increase in serum TNFα levels." (PMID 33997590, 2021). "Additionally, to determine whether RBO could improve the atherogenicity and insulin resistance status through attenuation in inflammation or not, the correlation of alterations in TNF-α serum concentration (ng/L) and various indices over the 8 weeks duration of the trial was examined." (PMID 34742318, 2021). "On the contrary the adiponectin/TNF-α ratio decreased in GDM and showed a negative correlation with insulin resistance." (PMID 29387323, 2018). "This meta-analysis suggested that circulating TNF-α levels in women with PCOS were significantly higher than those in healthy controls and that a high serum TNF-α concentration was related to insulin resistance and androgen excess but not to the BMI." (PMID 27764100, 2016). "In addition to adipocyte-derived factors, increased release of TNF-α, IL-6, monocyte chemo-attractant protein-1 (MCP-1) and additional products of macrophages and other cells that present in adipose tissue might also have a role in the development of insulin resistance." (PMID 25781947, 2015). "There is one study which reported that TNF-α system is activated in accordance with PP in normotensive type 1 diabetes mellitus, in which TNF-α system is a reflection not of insulin resistance but of inflammation." (PMID 25105150, 2014). "Anti-TNF treatment reduced DAS28 (P = 0.007), HAQ (P = 0.002), and CRP (P = 0.002) in patients with insulin resistance but not in those with HOMA-IR ≤ 2.0 (data not shown)." (PMID 22691241, 2012). "Taken together, results of the present study further bolster the hypothesis that TNFα is a key trigger in the onset of diet-induced non-obese MASLD and insulin resistance." (PMID 37683301, 2023).